BRCA1 (BRCA1 DNA repair associated)
Diseases named in the same sentence as BRCA1 in open-access papers (continued):
Sharing a sentence is not in itself a finding about the gene and the disease.
ovarian carcinoma (continued). "Here, we present the first prospective study in which liquid biopsy was used to assess and monitor the methylation status of the BRCA1 promoter during platinum‐based therapy in ovarian cancer patients." (PMID 34601813, 2021). "In patients with ovarian cancer, alterations in non-BRCA1 factors are involved in more than half of all cases with HRD." (PMID 36860287, 2021). "Women with a BRCA1 or BRCA2 mutation are at an increased risk of developing hereditary breast and ovarian cancers." (PMID 33804884, 2021). "BRCA1 and BRCA2, both of which help maintain genomic stability and are significantly mutated in ovarian cancer, directly interact with RAD51." (PMID 33952262, 2021). "The BRCA1 gene (MIM 113705), altered in terms of susceptibility to breast and ovarian cancers with a very high penetrance rate, is composed of 22 coding exons and two alternative non-coding exons (exons 1a and 1b)." (PMID 34202044, 2021). "Our analysis demonstrates that the concurrent low expression of BECN1 and BRCA1 is sufficient to make ovarian cancer cells more sensitive to chemotherapeutics." (PMID 33670664, 2021). "Germline mutations in BRCA1 and BRCA2 genes occur in up to 18% of patients with high-grade serous ovarian carcinomas (HGSOC), which are responsible for the vast majority of ovarian cancer deaths." (PMID 34202525, 2021). "By combining three studies by our group of the same cohort in Latvia, frequency of the BRCA1/2 PV for unselected breast and ovarian cancer cases is 241/5060 (4.8%) and 162/1067 (15.2%) respectively." (PMID 33468216, 2021). "Our data provide evidence that PAF-AH is a positive prognostic factor with functional impact, which seems particularly relevant in BRCA1 mutant ovarian cancer." (PMID 34206491, 2021). "BRCA1 promoter hypermethylation is frequently found in ovarian cancer and is often reversed upon recurrence, indicating the selection of therapy‐resistant clones and unfavorable clinical outcome." (PMID 34601813, 2021). "Mutations in BRCA1 or BRCA2 genes account for the majority of hereditary breast and ovarian cancers." (PMID 35008272, 2021). "For example, Wang’s study showed that with the progress of ovarian cancer, the methylation rate of the BRCA1 promoter increased significantly." (PMID 34289901, 2021). "Mutations in DNA repair genes BRCA1 and BRCA2 contribute to heredity to ovarian cancer and accordingly increase the genomic instability." (PMID 34721577, 2021). "Genotyping of 21 mutations in BRCA1, BRCA2, RAD51C, PALB2, and CHEK2 genes was performed for all 2270 ovarian cancer patients and 1743 healthy controls." (PMID 33670479, 2021). "Women who have inherited the BRCA1 or the BRCA2 mutation are at greater risk of developing breast and/or ovarian cancer." (PMID 35096615, 2021). "Mutations in the BRCA1 and BRCA2 genes are known risk factors and drivers of breast and ovarian cancers." (PMID 33525353, 2021). "Recently, Olaparib (a PARP inhibitor) was approved for treatment of BRCA1/2 breast and ovarian cancer as the first successful synthetic lethality-based therapy, showing considerable success in the development of effective targeted cancer therapeutics." (PMID 34070674, 2021). "Both patients initially exhibited ovarian cancer with a hypermethylated BRCA1 gene promoter, however, the status converted to presumably functional BRCA1 during the course of therapy." (PMID 34601813, 2021). "Of three PARP genes (PARP1–3) implicated in DNA repair, the highest expression of PARP1 was observed in germline BRCA1 carriers in both breast and ovarian cancers." (PMID 33525353, 2021). "Hypermethylation of BRCA1 in ovarian cancers correlate with significantly shorter median survival (n = 11, 35.6 months) compared to germline BRCA1 (n = 22, 78.6 months) and wild-type BRCA1 (n = 30, 63.3 months)." (PMID 34711195, 2021).
ovarian carcinoma (continued). "About 63% of BRCA1/2-mutant ovarian cancers will achieve a complete remission or partial remission after PARPi treatments." (PMID 34385422, 2021). "The risk of ovarian cancer has been well established in the BRCA 1 and 2 patient population, with lifetime estimates ranging from 22% to 65% for BRCA1 and 10% to 35% for BRCA2 mutation carriers." (PMID 34573353, 2021). "In the phase II study involving 32 patients with germline BRCA1/2 mutant platinum-sensitive ovarian cancer, the disease control rate (DCR) at 12 weeks was 81%, and the objective response rate (ORR) was 63%, with acceptable toxicity." (PMID 34712221, 2021). "Germline testing for LS in addition to BRCA1/2 for all women with an epithelial ovarian cancer would be efficient and would approach 100% sensitivity for identifying Lynch syndrome." (PMID 33369189, 2021). "HBOC is associated with pathogenic variants (PVs) in BRCA1 or BRCA2, where BRCA1 PVs are associated with a 39–63% lifetime risk of ovarian cancer and BRCA2 PVs are associated with a 15–27% risk." (PMID 33926482, 2021). "A combined analysis of two studies evaluating a PARP inhibitor in ovarian cancer demonstrated similar efficacy in germline BRCA1/2 mutant patients and somatic BRCA1/2 mutant patients." (PMID 33520111, 2021). "Assessing HRD status by the region of LOH has been proposed as a useful indicator for defective BRCA1/2, at least in ovarian cancer." (PMID 35008774, 2021). "CAPG and CAPN1 were found to be overexpressed in advanced stages of BRCA1-mutant ovarian cancers while PFN1, CFN1, and 14-3-3 were shown to be downregulated." (PMID 35008272, 2021). "Our findings on APEX2 are supported by evidence that this ZNF protein serves as a synthetic lethal target in BRCA1- and BRCA2-deficient colonic and ovarian cancer cell lines." (PMID 33962398, 2021). "Stefansson confirmed that BRCA1 hypermethylation increased platinum sensitivity in ovarian cancer cell lines, xenograft tumors and clinical samples." (PMID 34289901, 2021). "There were 17.1 ovarian cancers expected with 22 observed in BRCA1 PV carriers, and 6.25 expected and 10 observed in BRCA2 PV carriers." (PMID 33152107, 2021). "In parallel with the present work, a consensus guideline meeting on gynaecological cancer in LS recommended screening for LS in patients with endometrial and ovarian cancer (and also BRCA1/2 screening in ovarian cancer)." (PMID 34043773, 2021). "Somatic mutations of BRCA1/2 were also significantly associated with HRD in breast and ovarian cancers and these associations are already clinically exploited." (PMID 34572800, 2021). "High-grade serous ovarian cancer (HGSC) is the most common and aggressive type of epithelial ovarian cancer, with homologous recombination deficiency (HRD) and germline or somatic BRCA1/2 mutation being the high risk of oncogenesis." (PMID 34869593, 2021). "The different roles of BRCA1 and BRCA2 in genome protection confer distinct breast and ovarian cancer predisposition in mutation carriers." (PMID 34898566, 2021). "Overall, the distribution of age at ovarian cancer diagnosis was skewed to younger ages for women with PVs in BRCA1." (PMID 33926482, 2021). "Patients with BRCA1/2 mutant ovarian cancer are sensitive to platinum drugs, have a higher progression-free survival period, and have better prognosis." (PMID 34836507, 2021). "Ignatov's study showed that PFS was significantly prolonged in patients with BRCA1 promoter methylation in recurrent ovarian cancer (18.5 months vs 12.8 months, P = 0.008)." (PMID 34289901, 2021).
ovarian carcinoma (continued). "In another study, the upregulation of Polθ and its positive correlation with expression of many DNA repair genes including TOPBP1, BLM, RAD54L, FANCI, BRCA1, FANCD2, ATAD5 was reported in HR-deficient epithelial ovarian cancer cells." (PMID 34762643, 2021). "Pathogenic mutations of BRCA1 and BRCA2 genes are more frequent in ovarian cancer, but other genes are also related to this disease." (PMID 34547799, 2021). "Many of these cases have been attributed to germline mutations in BRCA1 and BRCA2 genes, which is a frequent molecular event in women with the most lethal and prevalent type of epithelial ovarian cancer, high grade serous ovarian carcinoma (HGSOC)." (PMID 34898566, 2021). "Diverse defects in HR DNA repair genes, such as germline mutations in BRCA1, BRCA2, and PALB2, somatic mutations in BRCA1 and BRCA2, and promoter methylation of BRCA1, have been reported in breast and ovarian cancers." (PMID 34249730, 2021). "A total of 3,127 index cases with breast and/or ovarian cancer have undergone testing for PGVs of BRCA1, BRCA2, PALB2, and CHEK2_c.1100delC." (PMID 34113003, 2021). "Between January 2009 and June 2020, 705 ovarian cancer patients underwent germinal BRCA1/2 gene test." (PMID 35071013, 2021). "PARPis have demonstrated substantial efficacy in BRCA1/2 breast and ovarian cancers until the point of tumor resistance, after which point progression of disease ensues, and the once effective therapy is essentially useless in affected patients." (PMID 34070674, 2021). "Silencing of its gene PLA2G7 caused activation of viability, proliferation, and migration of BRCA1 mutant ovarian cancer cells." (PMID 34206491, 2021). "The impact of germline mutations of BRCA1 and BRCA2 in breast and ovarian cancer are now well defined." (PMID 34830851, 2021). "According to previously findings, overexpression of CtBP2 was linked with abnormal proliferation, epigenetically silencing BRCA1 function, and poorer survival rate in ovarian cancer patients." (PMID 34253710, 2021). "Women with pathogenic germline mutations in BRCA1 and BRCA2 genes have an increased risk to develop breast and ovarian cancer." (PMID 34552867, 2021). "Patients and in vitro generated data indicate that PAF/PTAFR and PLA2G7/PAF-AH signaling plays a crucial role in BRCA1 mutant ovarian cancer." (PMID 34206491, 2021). "The ovarian cancer cluster region (OCCR) was identified in or near exon 11 in both the BRCA1 and BRCA2 genes." (PMID 34356066, 2021). "Reports suggest that the loss of heterozygosity (LOH) in the BRCA1 gene and DNA damage response (DDR) deficiency are strongly linked to the development of ovarian cancer." (PMID 34965417, 2021). "Inherited mutations in BRCA1 or BRCA2 genes predispose to breast and ovarian cancer, among other types of malignancies such as pancreatic cancers and brain tumors." (PMID 33879618, 2021). "This manuscript will review BRCA1/2 function and homologous recombination proficiency in respect to breast and ovarian cancer." (PMID 34711195, 2021). "Among 113 patients with strong family history for breast/ovarian cancer (HBOC), 18 (15.9%) were positive for heterozygous BRCA mutations (9 in BRCA1 and 9 in BRCA2)." (PMID 33726785, 2021). "The first part of the study investigated the impact of the publication of Australian clinical practice guidelines on use of BRCA1/2 germline testing for women with breast and/or ovarian cancer." (PMID 33836815, 2021). "Founder mutations in BRCA1 (nine alleles) and BRCA2 (four alleles) are frequent among Polish breast and ovarian cancer patients." (PMID 33670479, 2021).
ovarian carcinoma (continued). "In summary, by combining all three studies of the BRCA1/2 reported by our group, which are covering the same cohort, the PV frequency for unselected breast and ovarian cancer cases is 241/5060 (4.8%) and 162/1067 (15.2%) respectively." (PMID 33468216, 2021). "An important factor that contributes to ovarian cancer susceptibility is mainly represented in BRCA1 and BRCA2 genes that are associated with different risks of developing breast and ovarian cancers." (PMID 34930165, 2021). "From the point of view of therapy, finding germline variants in these proteins is also relevant, e.g., recent results indicate that BRCA1/2 testing helps design the treatment strategy for breast and ovarian cancer patients." (PMID 34207612, 2021). "In ovarian cancer, the prevalence of BRCA1/2 PVs is high and increases up to 23–25% in the high-grade serous histotype." (PMID 34572941, 2021). "For instance, in ovarian cancers bearing BRCA1/2 defects, TMB is higher if compared to BRCA1/2 wild-type tumors." (PMID 34944915, 2021). "In summary, the present study demonstrates that the concurrent low expression of BECN1 and BRCA1 is sufficient to make ovarian cancer cells more sensitive to chemotherapeutics." (PMID 33670664, 2021). "This study aimed to evaluate the prevalence and spectrum of 13 BRCA1 and BRCA2 founder mutations most frequently observed in the area of Central Europe in unselected patients from Belarus diagnosed with ovarian cancer." (PMID 33478551, 2021). "Both PLA2G7 expression on mRNA level (p < 0.05) and PAF-AH expression on protein level (p < 0.05) were significantly increased in the BRCA1 mutant ovarian cancer cell line UWB1.289 compared to HOSEpiC and other ovarian cancer cell lines." (PMID 34206491, 2021). "The aim of the study was to analyze the frequency and magnitude of association of 21 recurrent founder germline mutations in BRCA1, BRCA2, PALB2, RAD51C, and CHEK2 genes with ovarian cancer risk among unselected patients in Poland." (PMID 33670479, 2021). "BRCA1 and BRCA2 genes alteration are also associate with other cancer types such as ovarian cancer (16.5–27%), prostate cancer (15%), pancreas cancer (2–7%) and possible melanoma." (PMID 34828379, 2021). "Hypermethylation of the RASSF1A and BRCA1 promoters in circulating acellular tumor DNA is a biomarker for ovarian cancer." (PMID 33550277, 2021). "HBOC is caused by germline mutations mainly in the BRCA1 and BRCA2 genes; individuals with HBOC tend to have early onset of breast and/or ovarian cancer as well as some other types of cancer." (PMID 35070997, 2021). "Since PAF-AH mediates protective effects and is non-invasively detectable in blood samples, it should be considered a potential biomarker that indicates a good prognosis for patients with BRCA1 mutant ovarian cancer." (PMID 34206491, 2021). "The NOVA study demonstrated that niraparib improved survival of somatic BRCA1/2 mutant or BRCA normal but HRD positive by the Myriad myChoice CDx assay ovarian cancer." (PMID 34572800, 2021). "Methylation of the BRCA1 promoter is an epigenetic gene expression regulator and is frequently observed in ovarian cancer; however, conversion of methylation status is thought to drive disease recurrence." (PMID 34601813, 2021). "Initially, genetic testing was funded by state health departments, and individual family cancer clinics (FCCs) determined the criteria used locally to guide the offer of a BRCA1/2 genetic test to women affected by breast and/or ovarian cancer." (PMID 33836815, 2021). "By contrast, 39–44% of women who inherit a pathogenic BRCA1 variant and 11–17% of women who inherit the pathogenic BRCA2 variant will develop ovarian cancer by 70–80 years of age." (PMID 34207450, 2021).
ovarian carcinoma (continued). "The authors provided an historical view on BRCA1/2 testing performed in nearly 2000 breast/ovarian cancer patients extending from a first-tier BRCA1/2 population-based assay to next-generation sequencing (NGS) in a subset of patients." (PMID 34660253, 2021). "(EGFR and ALK in NSCLC, BRCA1 and BRCA2 in breast and ovarian cancer and homologous recombinant deficiency in prostate cancer)." (PMID 35047063, 2021). "In patients with ovarian cancer (OC) undergoing platinum‐based chemotherapy and PARP‐inhibitor treatment, BRCA1 deficiency is used as major predictive marker for estimating response to therapy." (PMID 34601813, 2021). "In ovarian cancers, we find an enhanced immune signature in somatic BRCA1 and germline BRCA2 carriers in agreement with previous reports, in which, however, differentiation between mutation types has not been explored." (PMID 33525353, 2021). "Our finding that BRCA2 mutations were significantly more frequent in the GR group is in accordance with evidence that mutations in BRCA1 and especially BRCA2, confer chemo‐sensitivity in ovarian cancer." (PMID 33811746, 2021). "In the OV_BRCA1 group, we observed overexpression of RCCD1, which was previously identified as a susceptibility locus for ovarian cancer, and of SUSD2, which promotes cancer metastasis and associates with cisplatin resistance." (PMID 33525353, 2021). "In the 891 RRBSO cases, there were 30 BRCA1 carriers (6.4%) who died during follow‐up, six due to ovarian cancer, five of whom were diagnosed at RRBSO, including three Stage 1 cancers and one post RRBSO PPC." (PMID 33152107, 2021). "The prevalence of PVs in BRCA1 or BRCA2 more than doubled within the subset of tested women with a history of ovarian cancer, with a combined prevalence of 6.1% (3.5% for BRCA1, 2.6% for BRCA2)." (PMID 33926482, 2021). "Retention of the normal BRCA1 or BRCA2 allele is observed in 7% and 16% of BRCA1 and BRCA2 germline mutation-associated ovarian cancers, and it is associated with decreased overall survival in patients treated with platinum chemotherapy." (PMID 33922503, 2021). "Defective Homologous Recombination Repair (HRR) function, e.g., due to BRCA1/2 loss, is a determinant of response to platinum agents and PARP inhibitors in ovarian cancers." (PMID 33804647, 2021). "The high-risk population in ovarian cancer are those with known genetic mutation such as BRCA1 and BRCA2 and those with known history of early-onset ovarian cancer in first degree relatives." (PMID 33477343, 2021). "Consistent with these clinical observations, our results demonstrate that either germline or somatic mutations in BRCA1/2 genes can be associated with HRD phenotype of breast and ovarian cancer." (PMID 34572800, 2021). "Mutated germline alleles in the DNA damage repair (DDR) genes “breast cancer gene 1” (BRCA1) and BRCA2 have originally been identified as major susceptibility genes in breast and ovarian cancers." (PMID 34707985, 2021). "Secondary malignancies were excluded, as the primary objective of the study was to reflect the frequency of BRCA1/BRCA2 PSVs in primary ovarian cancer patients." (PMID 34930165, 2021). "Pathogenic variants in the BRCA1 or BRCA2 genes are the most common cause of HBOC, and variant carriers have a 5- to 20-fold increased risk of developing breast or ovarian cancer." (PMID 34072979, 2021). "Women with pathogenic BRCA1 and BRCA2 mutations possess a high risk of developing breast and ovarian cancer." (PMID 34090422, 2021).